LINC01699 (long independently transcribed non-coding RNA 1699)
Synonyms: GM140
Gene: Long non-coding RNA gene on chromosome 1 (181,236,388 to 181,238,604, forward strand). Ensembl gene ENSG00000179452.
Diseases named in the same sentence as LINC01699 in open-access papers:
LINC01699 is named in the same sentence as 2 diseases in open-access papers, as found by Europe PMC text mining. Sharing a sentence is not in itself a finding about the gene and the disease.
LINC01699 shares sentences with these, for which no sentence is quoted: cancer (1 paper); tumor (1).